AKT1 (AKT serine/threonine kinase 1)
Diseases named in the same sentence as AKT1 in open-access papers (continued):
Sharing a sentence is not in itself a finding about the gene and the disease.
tumor (continued). "Several studies showed that Akt1 and Akt2 have opposite effects on tumor initiation and tumor progression." (PMID 34298660, 2021). "CircPLEKHM3 was identified to be downregulated in OC tissues, and it acted as a tumor suppressor in OC by sponging miR-9 to inactivate AKT1 and Wnt/β-catenin signaling pathways." (PMID 34367233, 2021). "AKT1 is a well known protein kinase that plays an important role in carcinogenesis by triggering tumor progression via the mammalian target of rapamycin (mTOR) signaling pathway." (PMID 34531452, 2021). "On the one hand, AKT1 is mainly involved in the promotion of tumor growth through regulation of cyclin D1, retinoblastoma protein (Rb), and p21." (PMID 33670586, 2021). "As substantial Akt1, Akt2 and Akt3 mRNA levels were detected in the majority of tumor samples of HNSCC patients, we can conclude that the target of MK2206 is present in HNSCC patients." (PMID 34568028, 2021). "Co‐expression of myr‐AKT1 and N‐RasV12 resulted in obvious liver enlargement and tumour burden within 4 weeks after injection in Mettl1‐KI group, resulting in significantly upregulation of liver weight to body weight ratio." (PMID 34898034, 2021). "Despite lack of total consensus, literature favors the possibility that AKT1 is involved in increased proliferation and tumor growth as well as decreased apoptosis, whereas AKT2 is associated with increased migration, invasion, and metastasis." (PMID 33498407, 2021). "AKT1 is involved in the regulation of many tumor processes, including tumor proliferation, cell survival, metabolism, growth, and angiogenesis." (PMID 33062007, 2020). "LINC01419 silencing inhibits the activation of the PI3K/AKT1/mTOR pathway, as demonstrated by reduced phosphorylation of AKT1 and mTOR, thus promoting autophagy of GC cells as well as inhibiting tumor growth and metastasis." (PMID 32754285, 2020). "Downstream of PI3K is AKT1, an important driver of the tumor glycolytic phenotype, which stimulates ATP production through a variety of mechanisms to ensure that cells have sufficient bioenergy to respond to growth signals." (PMID 32038983, 2020). "Since Akt1 depletion demonstrated the greatest effects on tumor growth and metastasis in the mouse models, we focused genes altered by depletion of Akt1." (PMID 33110146, 2020). "In the CTCs from CRC of advanced stages, epithelial markers, cell survival (AKT1), tumour suppressor and stemness genes were overexpressed." (PMID 33092235, 2020). "Concordantly, LASP1 knockdown inhibited cell migration and proliferation in several tumor entities and an indirect regulation of AKT1 by LASP1 was suggested." (PMID 32075106, 2020). "In summary, targeting PLK1 lead to a striking tumour regression in three out of fpur CCND1-driven PDX models, while AKT1 and mTOR mutated PDX preferably responded to AKT1 and mTOR inhibitors." (PMID 32792481, 2020). "MiR-185 acts as a tumor suppressor, and inhibits tumor progression by regulating its targets, including the Akt1 and PI3K/AKT pathway expression." (PMID 32915913, 2020). "The combination of SNPs with thehistopathological tumor data between allele variants of AMACR,AKT1+AR, and AKT1+AMACR indicated an associationwith protection against seminal vesicle invasion." (PMID 32484847, 2020). "The identification of tumor-initiating activities of AKT1 inspired the application of an AKT1 inhibitor to stimulate autophagy-associated HCC cell death." (PMID 33292207, 2020). "AKT1 plays a vital role in S100A9 downstream signal transduction pathway in favor of tumor progression, including PA." (PMID 33203795, 2020).
tumor (continued). "Germline deletion of Akt1 inhibited tumour development but had contrasting effects on metastasis where reduced, as well as increased, lung metastases has been reported in MMTV-neu mice." (PMID 33276499, 2020). "Previously, it is found that miR-409-3p has tumor suppressive role by binding to 3’ UTR of Akt1 and mediating its down-regulation." (PMID 33324567, 2020). "Conversely, administration of the ATG inhibitor 3-methyladenine (3-MA) or a recombinant full-length human active Akt1 protein (rAkt1) suppresses the anti-tumor effects of curcumin." (PMID 33092261, 2020). "The promoting effect on migration and invasion in cells with higher AKT1 activation depends on an activating crosstalk between astrocytes and the tumor cells via cytokines with autocrine and paracrine effects like BDNF and GM-CSF." (PMID 31752925, 2019). "CircNRIP1 can alter metabolism and autophagy through the AKT1/mTOR axis and promote tumour metastasis through exosome communication." (PMID 30717751, 2019). "There is also a very low apoptotic activity in residual tumor cells supported by very low expression of Bax and cleaved caspase 3 by residual tumor cells and high expression Bcl2 and AKT-1 by residual tumor cells." (PMID 30744593, 2019). "We proved that circNRIP1 sponges miR-149-5p to affect the expression level of AKT1 and eventually acts as a tumour promotor in GC." (PMID 30717751, 2019). "Given that PIK3CA and AKT1 genes promote proliferation and survival of tumor cells, their down-regulation by miRNAs results in a decline in the proliferation of cancerous cells." (PMID 34466540, 2019). "Isoginkgetin was reported as a general inhibitor of pre-mRNA splicing and can inhibit HT1080 tumor cell invasion by regulating PI3K/AKT1-dependent matrix metalloproteinase (MMP)-9 expression." (PMID 30995808, 2019). "In this experiment, animals treated with DEX combined with Akt2 or Akt1/2 inhibitor show significantly reduced tumor size similar to those observed in CCRF-CEM xenograft model." (PMID 30598523, 2019). "We and others have shown previously that microglia show direct cellular interactions with tumour cells and pre-neoplastic AKT1+ cells in the brain." (PMID 31313988, 2019). "Previous studies revealed that FALEC contributed to carcinogenesis by trans-regulating the expression of genes such as P21 and AKT1 involved in the malignant proliferation, invasion, and metastasis of tumor cells." (PMID 30984243, 2019). "As a consequence, AKT1 is supposed to play a crucial role in the initiation and progression of the primary tumor." (PMID 31752925, 2019). "All amplifications with copy numbers ≥8, except for AKT1, were detected in samples with 50% expected tumor purity." (PMID 31681791, 2019). "S6 was identified as another potential mediator for AKT1-specific induction of proliferation and in vivo tumor growth." (PMID 31752925, 2019). "Another protein that can act upstream and suppresses the tumor growth-stimulating AKT1 is miR-409-3p." (PMID 31752925, 2019). "It has been previously reported that AKT1-mediated β-catenin phosphorylation on Ser552 increased its transcriptional activity and promoted tumor cell invasion." (PMID 30918250, 2019).
tumor (continued). "Recently we showed that Akt1, the predominant Akt isoform in the PCa cells and tumor vascular cells plays a dual, reciprocal role in prostate tumor growth and metastasis." (PMID 31360736, 2019). "In our study, we proved that circNRIP1 sponges miR-149-5p to affect the expression level of AKT1 and eventually acts as a tumour promotor in GC." (PMID 30717751, 2019). "The studies performed to date on different in vitro tumor cell lines indicate that Akt1 most likely plays a differential and tumor cell type-specific role in the regulation of HRR." (PMID 31847370, 2019). "Further, AKT1 and RAPGEF1 were affected by phosphorylation, and MTOR is mutated to regulate downstream proteins involved in oncogenesis and tumor invasion." (PMID 31126066, 2019). "We have generated and characterized a novel Akt1/N-Ras-induced HCC mouse model which enables researchers to monitor tumor growth non-invasively." (PMID 30526672, 2018). "Several lines of evidence already supported that aberrant translational machinery such as modulation of ribosome biogenesis, Akt1/mTOR signaling and translational initiation play critical roles in tumor progression." (PMID 29568350, 2018). "Activating mutations in AKT1/2 results in accelerated tumorigenesis, however, AKT1 has an inhibitory effect on tumor cell invasion and migration, whereas AKT2 promotes metastasis." (PMID 29720957, 2018). "p-Akt1 expression was tested in a large cohort of cutaneous, oral, and sinonasal melanomas, and it was expressed in tumour cells and occasionally in inflammatory cells surrounding the tumour." (PMID 30647870, 2018). "The tumorigenic activity of p-Akt1 has also been investigated in several tumours and in the context of tumour cells, Akt1 upregulates cell proliferation, invasion, and migration." (PMID 30647870, 2018). "Collectively, these results strongly suggest that AKT1 activity promotes early stages of tumorigenesis but restricts the tumor cell metastatic potential." (PMID 29506489, 2018). "Through diverse signaling pathways, miR-149 targets Akt1, a gene that inhibits tumor cell apoptosis, thereby exerting its oncogenic potential." (PMID 29492228, 2018). "AKT1 promoter region was significantly hypo-methylated in tumor compared with matched normal tissue (P = 0.0014) in the 95 patients." (PMID 28301567, 2017). "A high level of activated Akt1 in tumor specimens is a prognostic factor for poor outcomes in NSCLC." (PMID 29156644, 2017). "AKT-1 acted as an inhibitor of germline tumor formation, as the shc-1;akt-1 double mutant shows tumor-like growth similar to that observed in shc-1;Is[daf-16::GFP]." (PMID 28549065, 2017). "Our results provide first-hand evidence that differences in the genetic background influences the role of AKT1 in tumor invasion and metastasis in NSCLC." (PMID 28765579, 2017). "Strikingly, Akt1 ablation in Pten+/- mice prevented the onset of neoplasia in endometrial, prostate and thyroid tissues, and reduced the incidence of intestinal polyps and high-grade neoplastic lesions in the adrenal medulla." (PMID 28082369, 2017). "The results showed that TCRP1, p-PDK1 and p-AKT1 were frequently overexpressed in tumor tissue samples compared with normal tissue samples." (PMID 28436990, 2017).
tumor (continued). "Subsequently, mice were harvested 28 weeks post hydrodynamic injection, when livers overexpressing myr-AKT1 exhibited tumor development." (PMID 28903330, 2017). "Average methylation level of the 10 CpG sites within 172 bp of AKT1 promoter region showed significant difference between the 95 tumor (7.49%) and matched normal tissues (8.35%) (P = 0.00144)." (PMID 28301567, 2017). "Pharmacological inhibition of DNA-PKcs or Akt restored radiosensitivity in tumour cells expressing Akt1-E17K or Akt1-TDSD." (PMID 28209968, 2017). "AKT1 showed significant difference of expression between tumor and normal tissue in TCGA but with higher expression in tumor." (PMID 28301567, 2017). "The AKT1 expression analysis showed that average gene expression level (dCt) of AKT1 in tumor is lower than normal tissues." (PMID 28301567, 2017). "In regards to kinase signaling, up-regulation on the protein level in the tumor was detected on both upstream and downstream of the mTOR including AKT1, PI3Kα, GRB2, mTOR, DPTOR, S6K and S6, which is known to be highly mutated in cancer." (PMID 29109428, 2017). "The Akt1 SH-siRNA has been found to suppress the Akt1 mRNA, decrease cellular proliferation and induce apoptosis in an in vivo mouse tumor model." (PMID 30970831, 2017). "In contrast to the effect of Akt1- and Akt3-knockdown, Akt2-knockdown significantly stimulated tumor growth." (PMID 29090098, 2017). "In FTCs, activation of AKT1 kinase and the localization of the protein in the nucleus promotes the PI3K/AKT pathway, contributing to tumor invasion and metastasis." (PMID 28117295, 2017). "eIF3i is shown to act as a signaling transducer by bind to and activating AKT1 through preventing PP2A-induced AKT1 dephosphorylation in tumor cells." (PMID 28193911, 2017). "The results of these studies propose an intra-tumour role for activated Akt1 as an important regulator of tumour progression and metastasis." (PMID 27661110, 2016). "Akt1 KD mice had the lowest (p<0.05) tumor microvessel density, while tumors generated with Akt2 KD cells had the highest density of blood vessels." (PMID 27533079, 2016). "There was increased expression in the HCC tumor compared to the benign adjacent tissue in the following proportions of HCCs: AKT1 (48.2%), AKT2 (29.1%) and AKT3 (70.0%)." (PMID 27611696, 2016). "Tumors from Akt1 null mice were significantly (p<0.05) smaller than all other groups at 60d post tumor induction." (PMID 27533079, 2016). "Akt1 KD had the highest (p<0.05), while Akt2 KD had the lowest (p<0.05) incidence of tumor cell apoptosis, while Akt3 KD tumors had less apoptosis than Akt1 KD tumors, but more than Akt2 KD." (PMID 27533079, 2016). "We found that loss of the tumor suppressors PTEN and INPP4B occurred with high frequencies in TNBC PDX, while PIK3CA and AKT1 mutations were rare." (PMID 27374081, 2016). "Recurrence analysis showed that patients with tumors expressing the highest versus lowest levels of AKT1 had a more rapid rate of tumor recurrence after surgical resection (P<0.05)." (PMID 27611696, 2016). "Ablation of Akt3, both in tumor cells and in the host often led to results that were intermediate between Akt1 and Akt2 knockdown." (PMID 27533079, 2016). "Western blots demonstrated that all the expression levels of Akt1 in tumor tissues were higher than that in normal tissues." (PMID 27323412, 2016). "For example, although both AKT1 and AKT2 are required for primary tumor growth, AKT2 appears to promote tumor metastasis, while AKT1 has an inhibitory role in tumor invasion and metastasis." (PMID 26895380, 2016). "Consistent with mRNA results, AKT1 protein levels in the tumor tissues derived from FHL2-overexpressing COV434 cells were significantly higher than that in tumor tissues derived from control COV434 cells." (PMID 27415427, 2016). "We recently described that AKT1 is involved in the regulation of ERβ expression, a tumor suppressor and positive prognostic factor in patients diagnosed with MPM." (PMID 26885609, 2016).
tumor (continued). "AKT1 mRNA levels in the tumor tissues derived from FHL2-overexpressing COV434 cells were significantly higher than that in tumor tissues derived from control COV434 cells." (PMID 27415427, 2016). "Although AKT1-mutant tumor specimens were often found to harbor concurrent alterations in other driver genes, a subset of specimens harboring AKT1E17K as the only known driver alteration was also identified." (PMID 27515171, 2016). "The selection of a pan-AKT inhibitor assumes that all 3 AKT isoforms promote tumor formation and progression, however, data from this current study and other studies suggest that AKT1 and AKT2 have opposite effects on lung tumorigenesis." (PMID 26654940, 2016). "Results from previous studies have suggested that the overexpression of AURKA increases the level of p-GSK-3β, p-Akt1 and β-catenin and plays an important role in cell proliferation, tumor progression and metastasis." (PMID 27121204, 2016). "Intriguingly, we also note a significant up-regulation of several tumor suppressors in AKT1(E17K) tumors, including neurofibromin 2 (NF2), PTEN and tuberous sclerosis 2 (TSC2)." (PMID 27004402, 2016). "We curated a dataset of mutations in AKT1-3 from COSMIC, TCGA, and individual tumor sequencing studies reported in the literature." (PMID 26701849, 2016). "Here, we showed that actein treatment suppressed the mRNA expressions of VEGFR1, CXCR4 and AKT1 in tumor tissues." (PMID 27731376, 2016). "Tumors generated with Akt1 KD ID8 cells had significantly (p<0.05) lower tumor cell proliferation compared to control or Akt2 or 3 KD tumors." (PMID 27533079, 2016). "Here, we assayed both virological factors and AKT1 activation in liver tissues obtained from HCC patients after tumour resection." (PMID 27779207, 2016). "Within the ID8 tumor cells, knocking down Akt1 resulted in a decrease in tumor size and metastasis 60 days post tumor induction and an increase in survival time." (PMID 27533079, 2016). "Our data demonstrate a role of the AKT1/SIRT1/FOXM1 axis in the expression of the tumor suppressor ERβ." (PMID 26885609, 2016). "In the present study, miR-495 has been demonstrated to be downregulated in ESCC tumor specimens and was negatively correlated with Akt1 protein levels." (PMID 27323412, 2016). "We found that neoplasia frequency went from 5.9% in uninduced flies (n = 119) to 0% in Akt1 RNAi induced flies (n = 124), coincident with decreased proliferation." (PMID 26607382, 2015). "AKT1 is especially noteworthy because its expression level in each tumor is consistently higher than in each normal sample by 2-4-fold." (PMID 26030765, 2015). "In endometrial PDX models harboring mutant AKT1-E17K and other tumor models with an activated AKT pathway, both compounds exhibited strong anti-tumor activity." (PMID 26469692, 2015). "Once activated, PI3K and its downstream effector AKT1 not only provide strong growth and survival signals to tumor cells, but also exert profound effects on their metabolism." (PMID 26208479, 2015). "A recent study has indicated that various miRNAs act as tumor suppressors and transiently transfecting cells with miR-331-3p reduced phosphorylated v-akt murine thymoma viral oncogene homolog 1 (AKT1) content." (PMID 24739220, 2014). "Terminal deoxynucleotidyl transferase–mediated dUTP nick end labeling and Ki67 immunostaining of lung tissue sections revealed that the delayed tumor induction in Akt1−/− mice was due to the inhibitory effects of Akt1 ablation on cell growth and survival." (PMID 24722238, 2014). "In contrast, AKT1 was most important for tumor initiation and progression in these mouse lung tumor models." (PMID 24946858, 2014). "Apoptosis assays indicated more apoptotic cells in Akt1−/− tumor cells than that in Akt1+/+ cells after doxorubicin treatment." (PMID 24658544, 2014). "Overexpression of CAM2KN1 in DU145 tumor tissues resulted in decreased ErbB2, AKT1, Bcl-2, NF-κB and AR mRNA levels and increased p21, Bax mRNA levels." (PMID 25003983, 2014).